CTC1 (CST telomere replication complex component 1)
Diseases named in the same sentence as CTC1 in open-access papers (continued):
Sharing a sentence is not in itself a finding about the gene and the disease.
Werner syndrome (1 paper, 2018). "In this study, we report two families with novel CTC1 variants in patients referred to the International Registry of Werner Syndrome who were ascertained because of signs of accelerated aging." (PMID 30393977, 2018). "We identified two pedigrees with progeroid features carrying novel CTC1 variants among cases referred to the International Registry of Werner syndrome." (PMID 30393977, 2018).
cancer (12 papers, 2010 to 2025). A tumor composed of atypical neoplastic, often pleomorphic cells that invade other tissues. "Results gleaned from overexpression studies of human CP mutations in HCT116 cancer cells and expressing corresponding human CTC1 mutations into CTC1−/− MEFs strongly suggest that CP is due to failure to properly maintain the telomeric C‐strand, leading to telomere replication defects." (PMID 29774655, 2018). "First, tumors have less CTC1/STN1 but more TEN1 expression than their adjacent normal tissues in a majority of cancer types." (PMID 35368664, 2022). "Cox regression revealed that CTC1, STN1, the CS score, and the CST score were associated with better survival in at least four cancer types, while TEN1 was associated with worse survival only in LGG." (PMID 35368664, 2022). "Among cancer patients, those of early stage showed higher CTC1 expression than those of late stage (P = 3.51e−03, t-test)." (PMID 28009993, 2017). "Cdc13 and its putative homologues human CTC1 and POT1 are therefore key to many biological processes directly associated with life extension and cancer prevention and can be viewed as an ideal target for cancer and age related therapies." (PMID 20975208, 2010). "Knockdown of either Stn1 or Ctc1 in human cancer cells and in mouse fibroblasts results in substantially elongated telomeric G-overhangs, consistent with its recently demonstrated role in facilitating telomeric C-strand synthesis and negatively regulating telomerase." (PMID 25684230, 2015). "Likewise, further studies on the role of CTC1 in regulating radiosensitivity in other radiosensitive-radioresistant cancer cell lines are another avenue to pursue." (PMID 24718655, 2014). "Supporting this, tumors with high a level of CTC1 and STN1 display low levels of telomerase activity, cancer stemness (an indicator of cancer progression), and genome instability." (PMID 35368664, 2022). "We found telomere maintaining genes (TERF2, CTC1, and ACD), genes involved in zinc homeostasis (MTF1 and SLC30A9), transcription elongation factor complex components (ICE1, ICE2, ELL), and BCL6 corepressors (BCOR, BCORL1) uniquely invoked in TNBC cancers." (PMID 40700427, 2025). "Collectively, these findings suggest that non-coding RNAs might be responsible for the suppression of CTC1 and STN1 in cancer." (PMID 35368664, 2022). "Besides this, rare and potentially pathogenic variants were identified in the DNA repair gene POLN and other cancer-related genes such as PPARG, CTC1, DCC and ALPK1." (PMID 36077770, 2022). "Interestingly, by mining the miRNA-target interaction database and analyzing the correlation between miRNA and CST expression, we found that CTC1 and STN1, but not TEN1, could be repressed by multiple miRNAs in various cancer types." (PMID 35368664, 2022).
tumor (6 papers, 2014 to 2022). "When comparing the expression of CST between tumor and paired adjacent normal samples, we found that CTC1 and STN1 were largely downregulated, whereas TEN1 was upregulated in tumors." (PMID 35368664, 2022). "The primary tumor resection showed a significant correlation with CTC1 presence (p = 0.019)." (PMID 30189880, 2018). "However, in our current study, the pro-apoptotic activity of anti-CTC1 in tumor cells makes it difficult to establish a stable clone to constitutively suppress CTC1." (PMID 24718655, 2014). "Consequently, CTC1 regulation by miR-376a-3p may provide adaptive mechanisms for understanding the tumor progression." (PMID 33937245, 2021). "Moreover, tumor genes including c-Myc, KLF15, and NRP1 were reported to be targeted by miR-376a, which may explain why the re-expression of CTC1 cannot fully rescue the miR-376a overexpression-induced defects." (PMID 33937245, 2021). "This positive correlation data suggest that DNA methylation was not responsible for the downregulation of CTC1 and STN1 expression in tumor samples." (PMID 35368664, 2022). "Our work suggests that CTC1 and STN1, but not TEN1, are putative tumor suppressors." (PMID 35368664, 2022).
genetic disorder (1 paper, 2014). "Mutations in CTC1 underlie the rare human genetic disorder, Coats plus, characterized by gastrointestinal and neurological defects, as well as shortened telomeres and evidence of an ongoing DNA damage response." (PMID 24718655, 2014).
CTC1 also shares sentences with these, for which no sentence is quoted: retinal telangiectasia (2 papers); adenocarcinoma (1); atrial fibrillation and flutter (1); atrial septal defect (1); brain tumors (1); breast invasive cancer (1); cardiovascular disease (1); colon adenocarcinoma (1); colorectal cancer (1); dementia (1); diffuse large B-cell lymphoma (1); ependymoma (1); haematological disorders (1); kidney chromophobe (1); lung adenocarcinoma (1); lung squamous cell carcinoma (1); lymphoid neoplasm (1); malignant mesothelioma (1); mesothelioma (1); non-melanoma skin carcinoma (1); normocytic anaemia (1); oligodendroglioma (1); optic atrophy (1); ovarian carcinoma (1); prostate adenocarcinoma (1); prostate carcinoma (1); retinal angioma (1); uterine corpus endometrial carcinoma (1); uterine serous carcinoma (1).